IGF1 (insulin like growth factor 1)
Diseases named in the same sentence as IGF1 in open-access papers (continued):
Sharing a sentence is not in itself a finding about the gene and the disease.
acromegaly (continued). "IGF-1 level is used more often for routine diagnosis of acromegaly as it is stable during the day." (PMID 33849304, 2021). "In 25/53 patients (47.2%), IGF-1 levels were evaluated because of clinical suspicion of acromegaly." (PMID 34081617, 2021). "Other than acromegaly different conditions influence IGF‐1 activity in cats." (PMID 33830548, 2021). "All preoperative acromegaly patients had IGF-1 levels above the clinical RR." (PMID 33671326, 2021). "The most important assays for the diagnosis and management of acromegaly are GH and IGF-1 levels." (PMID 33803429, 2021). "Thus, octreotide is used for the treatment of GH/IGF-1-related diseases, such as acromegaly, TSH-secreting pituitary adenomas, and gastro-entero and pancreatic neuroendocrine tumor." (PMID 33886620, 2021). "Our findings suggested that long-term persistent and excess serum GH/IGF-1 levels alter the microstructure in the cortex and white matter in acromegaly, which may be responsible for neuropsychological dysfunction." (PMID 33912457, 2021). "IGF-1 levels were significantly higher in patients with acromegaly (p<0.001)." (PMID 35059575, 2021). "To date, however, the impact of long-term and persistent excess serum GH/IGF-1 levels on cortical and white matter microstructures, such as myelin and neural fibers, has largely remained unknown in acromegaly." (PMID 33912457, 2021). "Therefore, apart from the influence of excessive GH and IGF-1, acromegaly patients also suffer from hyperprolactinemia and hypopituitarism, causing comorbidities and worsening their quality of life and prognosis." (PMID 35154007, 2021). "Notably, this hormone usually declines with age, although metabolic abnormalities and acromegaly leads to IGF1 increase." (PMID 33692752, 2021). "According to a recent consensus statement on multidisciplinary management of acromegaly IGF-1 values up to 1.2–1.3× ULN range may also be considered sufficient for control of acromegaly." (PMID 33803429, 2021). "All patients met clinical criteria for acromegaly and presented with elevated IGF-1 levels." (PMID 34867787, 2021). "In patients with clinical features suggestive of acromegaly, elevated IGF-1 is usually sufficient to complete the diagnosis, and the OGTT may be used as a confirmatory test." (PMID 33803429, 2021). "Furthermore, it has been found that IGF-1 levels in subretinal fluid are extremely high in patients with acromegaly." (PMID 35059575, 2021). "Acromegaly is a rare, chronic, and systemic disease characterized by an excessive production and secretion of growth hormone (GH), resulting in high circulating levels of insulin-like growth factor 1 (IGF-1)." (PMID 34025586, 2021). "Notably, in this study, most patients treated with injectable SRLs and considered well controlled (IGF-1 ≤1.3 × ULN) experienced acromegaly symptoms despite being biochemically controlled on medical treatment." (PMID 33790860, 2021). "In our present study, we hypothesized that the excess of GH/IGF-1 affects directly or indirectly the bone remodelling of the periodontal tissue in acromegaly patients." (PMID 33421969, 2021). "However, fg-SRL treatment has well-recognized positive effects in patients with acromegaly, both in terms of absolute and relative GH and IGF-1 reduction, achievement of biochemical control (about 30-50% of cases), as well as tumor volume reduction." (PMID 34025586, 2021). "IGFBP-3 levels may assist in the diagnosis and monitoring of acromegaly as there is a direct correlation between IGFBP-3 levels with IGF-1." (PMID 33803429, 2021). "Besides, negative correlations between serum asprosin levels and the course of acromegaly, IGF-1 SDS, GH-Nadir, and GH-AUC in acromegaly patients were observed." (PMID 33414826, 2020). "An elevated level of GH in acromegaly stimulates the liver to synthesize increased levels of IGF-1." (PMID 32670201, 2020). "Acromegaly is characterized by Growth Hormone (GH) and Insulin-like Growth Factor 1 (IGF-1) excess." (PMID 32458292, 2020).
acromegaly (continued). "Likely, the risk of apparent CAD is a consequence of concomitant traditional CVD risk factors rather than direct effects of GH or IGF-1, and consequently, acromegaly treatment reduces risk of CAD via amelioration of CVD risk factors." (PMID 32458292, 2020). "Reductions in IGF-1 (− 6.453 vs − 7.003) and GH levels (− 9.548 μg/L vs − 13.182 μg/L), and the proportion of patients with ≥1 acromegaly symptom (− 20.3% vs − 32.5%) were observed from baseline to end-of-study in lanreotide autogel and lanreotide 40 mg PR groups, respectively." (PMID 32366244, 2020). "All our patients with acromegaly had hypogonadism, possibly due to the compressive effect of macroadenoma on surrounding gonadotropes and/or concurrent hyperprolactinemia, thereby mitigating the protective effects of GH/IGF1 on periodontal health." (PMID 33154456, 2020). "Moreover, a 2013 study of 71 patients with acromegaly found that patients with severe arthropathy (n = 19) had significantly lower levels of IGF-1 (and higher body mass index) than patients with less severe arthropathy (n = 21)." (PMID 31741320, 2020). "Both random GH levels and IGF-1 levels were elevated in patients with acromegaly." (PMID 33414825, 2020). "As such, GH and IGF-1 are biochemical markers of acromegaly activity." (PMID 32882036, 2020). "In this study, we used CMR to investigate the frequencies of cardiac abnormalities and detailed quantitative cardiac parameters in acromegaly patients and then analyzed the correlations between the changes in cardiac structure and function and patients' clinical indexes and GH and IGF-1 levels." (PMID 32148485, 2020). "In this trial, maintenance of mean IGF-1 levels for the OOC group (n = 28) from baseline to end of treatment indicates that patients who switched from injectable SRLs to OOCs retain biochemical control of acromegaly." (PMID 32882036, 2020). "In this context, the aim of the present cross-sectional, multicentre study was to determine the effectiveness, as measured by IGF-1 levels, of lanreotide autogel 120 mg administered at dosing intervals >4 weeks for more than 6 months in patients with acromegaly treated in routine clinical practice." (PMID 32725444, 2020). "Serum GH, IGF1, HbA1c, pituitary hormones and MRI sella were performed in patients with acromegaly." (PMID 33154456, 2020). "It is suggested that this concept may also apply to acromegaly, since GH and IGF-1 have repeatedly been reported to impact on the immune system." (PMID 32458292, 2020). "Given the strong relation between the RDI and IGF-1 levels, it is not expected that patients in stable remission of acromegaly would develop OSAS, as long as other risk factors for development of OSAS are not present." (PMID 31612224, 2020). "Acromegaly is a disease due to chronic GH excess and a consequent rise in IGF-1 levels." (PMID 32117056, 2020). "Excess GH and IGF-1 can also result in changes in the body composition of patients with acromegaly." (PMID 33414825, 2020). "Elevated serum IGF-1 is the recommended biomarker for diagnosing acromegaly." (PMID 31741320, 2020). "Despite achieving biomedical control as defined by normal IGF-1 and GH levels, acromegaly symptoms may persist." (PMID 32221764, 2020). "Indeed, acromegaly treatment resulting in IGF-1 normalization is reported to reduce the RDI/AHI and tongue volume, and IGF-1 levels correlated with tongue volume." (PMID 31612224, 2020). "Higher GIP levels in patients of acromegaly could have possibly resulted from the direct cytotrophic effect of elevated GH/IGF-1 on K-cells." (PMID 30948746, 2019). "Focusing on cortical thickness, CBTneck correlated with GH levels and CBTcalcar with IGF‐1 levels at baseline in acromegaly, but not in NFPA, whereas this association was absent at 1 year in both groups." (PMID 31844828, 2019). "The IGF-1 level is considered positively correlated with BMD in patients with acromegaly." (PMID 31781204, 2019).
acromegaly (continued). "Acromegaly is a neuroendocrine disease characterized with acral enlargement, growth hormone (GH) hypersecretion, increased levels of insulin-like growth factor 1 (IGF-1), and most the result of a pituitary tumor producing GH." (PMID 31771524, 2019). "Suppression of the GH/IGF1 axis is a key medical therapy that is indicated for acromegaly and may also be useful in other diseases such as cancer." (PMID 30775002, 2019). "We cannot say that whether increased SOS values in acromegaly patients are due to fibrosis or to IGF-1 effects at cellular level." (PMID 30653179, 2019). "Acromegaly is a rare (incidence of 3.3 per million per year), chronic, multisystem disease characterized by excessive growth hormone (GH) secretion and elevated insulin-like growth factor-1 (IGF-1) levels." (PMID 30269264, 2019). "In addition, elevated GH/IGF-1 levels and longer duration of acromegaly tended to positively correlate with these changes." (PMID 31939489, 2019). "The glucagon levels before surgery were significantly higher in patients with hyperglycaemia than in euglycaemic subjects with acromegaly, and the levels decreased significantly after surgery in both the groups in parallel to the significant reduction in IR and GH/IGF-1 levels." (PMID 30948746, 2019). "In a report of 3 patients treated with pegvisomant, linear growth was interrupted after 6 months of treatment, and improvement in diaphoresis and facial features of acromegaly was observed, along with normalization of IGF-1 levels in 2 of them, while the other one showed an increase in tumor size." (PMID 31365626, 2019). "The higher glucagon levels in patients of acromegaly could have possibly resulted from the direct cytotrophic effect of elevated GH/IGF-1 on pancreatic α-cells." (PMID 30948746, 2019). "We also evaluate whether classifications of disease-control status align with disease activity, hormonal control (GH and IGF-1 levels obtained from routine hormone assays), and treatment decisions in acromegaly." (PMID 31338660, 2019). "PEGV effectiveness in normalizing IGF-1 levels in patients with acromegaly is highly variable." (PMID 31460622, 2019). "Therefore, significant risk factors included a presence of an adenoma on initial screening but also elevated growth hormone or serum IGF-1 levels, i.e., uncontrolled acromegaly." (PMID 31293513, 2019). "Therefore, it can be concluded that the elevated lumbar-spine BMD in patients with acromegaly recovered to normal levels after surgery when the GH and IGF-1 levels were controlled." (PMID 31781204, 2019). "Interestingly, the Liege Acromegaly Survey, based on 3173 patients, noted a significant relationship between glucose levels and IGF-1 concentrations." (PMID 30474822, 2019). "Moreover, patients with normal serum IGF-1 levels had smaller thyroid glands than those in patients with active acromegaly." (PMID 31477080, 2019). "Interestingly, IGF-1 mediates physiological hypertrophy of heart muscle, but an excess of IGF-1 can lead to cardiac dysfunction, as shown in acromegaly, a disease characterized by excessive production of GH which stimulates massive release of IGF-1." (PMID 30443216, 2018). "Acromegaly may present with high levels of growth hormone and varying levels of IGF-1 and similar lung structure and functions compared with health controls, and none of the lung functional, radiological, and biological findings correlated with IGF-1 levels." (PMID 30018981, 2018). "In women with mild acromegaly, oral contraceptives may normalise IGF-1 and reduce metabolic and body compositional effects of GH excess." (PMID 29849625, 2018). "Acromegaly was also excluded based on normal Insulin-like growth factor-1 (IGF1)." (PMID 30376853, 2018). "In acromegaly patients, the average serum IGF-1 level is about 676 ng/mL and may reach 1000 ng/mL, meaning that it can increase from approximately 1.5-fold to 10-fold." (PMID 30336646, 2018).
acromegaly (continued). "Echocardiographic and plasma IGF-1 measurements before and after treatment of acromegaly." (PMID 29596445, 2018). "Acromegaly is a hormonal disorder resulting from excessive growth hormone (GH) secretion frequently produced by pituitary adenomas and consequent increase in insulin‐like growth factor 1 (IGF‐I)." (PMID 29266696, 2018). "Therefore, the main therapeutic goal in acromegaly is the reduction in circulating GH and IGF‐1 circulating levels." (PMID 29266696, 2018). "The way GH and IGF-1 are measured and reported in acromegaly research varies considerably." (PMID 29605877, 2018). "In agreement with this, our acromegaly model showed a significant increase in liver IGF-1." (PMID 30336646, 2018). "Acromegaly is a hormonal disorder resulting from excessive growth hormone (GH) secretion frequently produced by pituitary adenomas and a consequent increase in circulating hepatic insulin‐like growth factor 1 (IGF‐I)." (PMID 29266696, 2018). "The insulin-like growth factor 1 (IGF-1) levels in the acromegaly patients were linearly and positively correlated with the nose width (p = 0.006) and gonion-gnathion distance (p = 0.029) and linearly and negatively correlated with the nasofrontal angle (p = 0.026)." (PMID 30555420, 2018). "Our acromegaly model showed a four-fold increase in liver IGF-1 mRNA level and a five-fold increase in IGF-1 mRNA level at the larval stage, indicating that our acromegaly model IGF-1 level may resemble the acromegaly IGF-1 level." (PMID 30336646, 2018). "Moreover, adiponectin levels were inversely related to serum IGF-1 in acromegaly, suggesting that both IGF-1 and BMI are determinant factors affecting circulating adiponectin levels in patients with active disease." (PMID 29036907, 2017). "The diagnosis of acromegaly is made when elevated IGF-1 is associated with the “absence of GH suppression” during an OGTT." (PMID 28977166, 2017). "Acromegaly is characterized by changes in concentrations and actions of GH, IGF-1 and insulin." (PMID 27568329, 2017). "Third, the diagnosis of acromegaly is confirmed when elevated IGF-1 is associated with lack of GH suppression during an oral glucose tolerance test (OGTT)." (PMID 28977166, 2017). "Again, this suggests that IGF-1 levels may be a better representation of the activity of acromegaly overall." (PMID 28733467, 2017). "Similar to acromegaly, bGH mice have elevated plasma levels of GH and IGF-1." (PMID 28933734, 2017). "However, patients with persistently elevated IGF-1 clearly had a high prevalence of several acromegaly symptoms and comorbidities." (PMID 28898247, 2017). "Our result was in agreement with this finding and demonstrated that IGF-1 levels played a critical role in the process of pharyngeal hypertrophy and respiratory tract stenosis as well as contributed to a higher incidence of DI in patients with acromegaly." (PMID 28620866, 2017). "One could also argue that the 5 cases with persistently elevated IGF-1, particularly the one with a pituitary microadenoma are in fact, acromegaly cases." (PMID 28898247, 2017). "Moreover, the two acromegaly cases (as well as the other 5 patients with persistently high IGF-1), had at least one acral symptom and three or more other typical acromegaly symptoms." (PMID 28898247, 2017). "Remarkably, patients with persistently elevated IGF-1 had a higher prevalence of typical acromegaly symptoms and comorbidities (100% had ≥3), and the number of acral as well as other acromegaly symptoms was significantly higher than in the rest of population studied." (PMID 28898247, 2017). "Balili and Barkan evaluated hormonal effects of the SERM tamoxifen in 15 male acromegaly patients with active disease and 2 post-menopausal women, also with biochemically-active acromegaly despite the fact that other modalities were ineffective in normalizing their IGF-1 levels." (PMID 27568329, 2017).
acromegaly (continued). "The first-generation somatostatin analogues, octreotide and lanreotide, are currently the medical treatment of choice in acromegaly, as both adjuvant and first-line therapy, and have demonstrated efficacy in controlling GH and IGF-1 levels and in reducing pituitary tumor volume." (PMID 26290466, 2016). "Our results show that even in patients with a suggestive clinical scenario and elevated IGF-1, confirmed in a second measurement and without apparent cause, acromegaly is very unlikely in the case of GH suppression in the OGTT." (PMID 27982199, 2016). "Therewith the therapeutic plan aims to control tumor growth, normalize, or reduce hormonal hypersecretion of GH and IGF-1, but also a long-term goal is to reduce the rates of morbidity and mortality, which are much higher in patients with acromegaly compared to the general population." (PMID 27453753, 2016). "This fact may explain, at least in part, the higher concentrations of IGF-1 in some patients with acromegaly (for a given concentration of GH), or the greater increase in IGF-1 seen in some patients during treatment with GH." (PMID 27982199, 2016). "Additionally, serum IGF-1 levels are elevated in patients with acromegaly because of increased production from the liver." (PMID 27517036, 2016). "The two parameters of biochemical control, suppression of excess GH secretion to predefined threshold levels and normalization of serum IGF-1 levels, are used as the primary markers of efficacy in most clinical trials of somatostatin analogues in patients with acromegaly." (PMID 26519143, 2016). "Because many patients with uncontrolled acromegaly are undiagnosed for years, it is possible that persistently elevated GH and IGF-1 levels could be a factor in the relatively high incidence of colon cancer in this cohort compared with the general population." (PMID 28025627, 2016). "Repeated colonoscopic screening of patients with acromegaly has demonstrated a high prevalence of new adenomatous and hyperplastic colonic polyps, dependent on both the occurrence of previous polyps and elevated IGF-1 levels." (PMID 27279011, 2016). "In this study, 24 acromegaly patients took long-acting somatostatin analogue for 3 to 6 months preoperatively, which caused the shrinkage of tumor and notable reduce of GH and IGF-1 levels while tumor invasiveness showed no change." (PMID 27899081, 2016). "We therefore believe that the combination of these findings (persistent suppression of GH, absence of the occurrence of phenotypic features or changes in physiognomy and of an increase in IGF-1 after 5 years) renders acromegaly highly unlikely in these two cases." (PMID 27982199, 2016). "In a large, randomized, double-blind, Phase III trial (core phase of this study), pasireotide long-acting release (LAR) was significantly superior to octreotide LAR at providing GH <2.5 μg/L and normal IGF-1 at month 12 in medically naïve patients with acromegaly." (PMID 27039081, 2016). "The finding of elevated IGF-1 outside puberty and pregnancy strongly supports the hypothesis of acromegaly." (PMID 27982199, 2016). "IGF-1 exerts effects on numerous target tissues throughout the body, and stimulation via this growth factor contributes to the increased morbidity and mortality encountered in patients with acromegaly." (PMID 27517036, 2016). "If acromegaly is suspected IGF-1 measurement and a GH suppression test will be performed." (PMID 27349224, 2016). "Assessing PROs in acromegaly patients treated with other medical treatments may shed more light on the etiology of symptoms and their possible mediation by IGF1 effects vs GH effects." (PMID 26744896, 2016). "As expected, the treatment-naïve active acromegaly patients had significantly higher IGF1, marginally elevated but insignificant LDL, triglyceride (TG), hsCRP, BMC, BMD, TBF, LBM, and LV-mass as compared with acromegaly patients with GHD at baseline and even after treatment." (PMID 25600246, 2015).